TLR2 (toll like receptor 2)
Diseases named in the same sentence as TLR2 in open-access papers (continued):
Sharing a sentence is not in itself a finding about the gene and the disease.
intestinal cancer (3 papers, 2012 to 2022). "The EPS extracted from Lactobacillus plantarum NCU116 showed the ability to induce apoptosis in intestinal cancer cells by elevating the expression of proapoptotic genes, including c-Jun, Fas, and FasL, by targeting the Toll-like receptor-2 (TLR-2)." (PMID 36005587, 2022). "Previous studies indicate a protective role of TLR2 in the development of intestinal cancers." (PMID 22442665, 2012).
kidney injury (3 papers, 2014 to 2025). Trauma to the kidney. "Specifically, TOLLIP suppressed TLR2/4-NF-κB signaling to protect against PQ-induced NLRP3 inflammasome activation, thus attenuating kidney injuries." (PMID 35720190, 2022).
Klebsiella Infections (3 papers, 2015 to 2020). Infections with bacteria of the genus KLEBSIELLA. "In addition, TLR4–/– × TLR2–/– mice were also observed to be more susceptible to Klebsiella infection." (PMID 32670220, 2020). "Interestingly, cooperative roles of TLR4 and TLR2 signalling are involved in controlling Klebsiella infection because TLR4−/−xTLR2−/− mice are more susceptible to the infection than each of the single knock-out mice." (PMID 30452654, 2019). "TLR4, TLR2, and TLR9 signaling have been shown to play an important role in Klebsiella infection recognition and defense." (PMID 32670220, 2020).
malignant brain tumors (3 papers, 2021 to 2023). "25-HC also promotes cell migration and invasion in lung, gastric, and brain cancers by activating a G protein-coupled receptor or the Toll-like receptor 2 (TLR2)/NF-kB pathways and the LXR/interleukin-1B (IL-1B) signaling pathway." (PMID 37653037, 2023). "Eight PRRs were identified as up-regulated after the second immune challenge, including perlucin 4, C1q domain containing protein 2, scavenger receptor class B-like protein, deleted in malignant brain tumors 1 protein-like, TLR, TLR2, TLR3 and TLR8." (PMID 34295333, 2021).
mantle cell lymphoma (3 papers, 2014 to 2025). Mantle cell lymphoma is a rare form of malignant non-Hodgkin lymphoma affecting B lymphocytes in the lymph nodes in a region called the ``mantle zone''. "In chronic lymphocytic leukemia (CLL), low TLR2 expression is linked to a poor prognosis, while in mantle cell lymphoma (MCL), TLR4 signaling can trigger tumor growth." (PMID 40922674, 2025). "In mantle cell lymphoma, TLR2 promotes the proliferation of tumor cells, and it can also inhibit the cell cycle progression of mantle cell lymphoma, leading to G1 phase arrest." (PMID 32256204, 2020). "In mantle cell lymphoma (MCL), TLR1, TLR4, TLR7, TLR9 and TLR10 exhibit significant mRNA levels, whereas TLR2, TLR3, TLR5 and TLR8 are negative." (PMID 25112836, 2014).
Neonatal sepsis (3 papers, 2023 to 2026). Systemic inflammatory response to infection in newborn babies. "Notably, TLR2-dependent IL-10 production was shown to impair immune cell recruitment to infected tissues during GBS neonatal sepsis and neonatal mice deficient in TLR2 exhibited reduced levels of IL-10 upon GBS infection that were ultimately associated with bacterial clearance." (PMID 37747229, 2023). "(i) It is an innovative study that directs the spotlight onto the effect of the presence of TLR2, TLR4, IL6, and IL10 polymorphisms in the context of early neonatal sepsis in preterm neonates." (PMID 41598258, 2026).
neuropathy (3 papers, 2016 to 2025). A disorder affecting the nervous system that manifests with pain, tingling, numbness, and/or muscle weakness. "What is more, TLR2 or TLR4 deficient animals with induced neuropathy are more resistant to pain." (PMID 26962463, 2016). "Summing up, in light of their upregulation over the course of pain, both TLR2 and TLR4 may indeed play a significant role in neuropathy, which could be linked to the observed activation of IBA-1/CD40-positive cells." (PMID 26962463, 2016). "In the CNS, TLR2, and TLR4 are predominantly expressed on glial cells, with the greatest importance in the context of neuropathy on microglia." (PMID 28491822, 2017). "This implies that the only change that can be observed in the DRG occurs at the beginning of neuropathy progression, so it can be assumed that the response of TLR4 to the injury state in the DRG is faster than that of TLR2." (PMID 26962463, 2016). "Biochemical analysis revealed time-dependent upregulation of mRNA and/or protein levels of TLR2 and TLR4 and MyD88 and TRIF adaptor molecules, which was paralleled by an increase in IBA-1/CD40-positive cells under neuropathy." (PMID 26962463, 2016). "In our experiment, TLR2 and TLR4 were also upregulated in DRG tissue at all of the time points measured after CCI-induced neuropathy." (PMID 26962463, 2016). "The TLR antagonists LPS-RS (TLR2 and TLR4) and LPS-RS Ultrapure (TLR4) similarly diminished pain behavior after CCI, suggesting a greater contribution of TLR4 in neuropathy, at least in the rat nerve injury-induced neuropathic pain model." (PMID 26962463, 2016). "In the central nervous system, TLR2 and TLR4 are expressed predominantly on glial cells, and for neuropathy, the most relevant expression is on microglia." (PMID 26962463, 2016). "Experiments were conducted to evaluate the contribution of TLR2 and TLR4 and their adaptor molecules to neuropathy and their ability to amplify opioid effectiveness." (PMID 26962463, 2016).
non-Hodgkin lymphoma (3 papers, 2016 to 2025). Distinct from Hodgkin lymphoma both morphologically and biologically, non-Hodgkin lymphoma (NHL) is characterized by the absence of Reed-Sternberg cells, can occur at any age, and usually presents as a localized or generalized lymphadenopathy associated with fever and weight loss. "For example, a clinical trial treating 11 patients with non-Hodgkin’s lymphoma showed that tandem of a Toll-like receptor 2 (TLR2) TIR structural domain in a CD28-based CAR structure targeting CD19 resulted in severe CRS in 2 patients (18%) and severe ICANS in 1 patient (9%) (NCT04049513)." (PMID 40181986, 2025).
otitis (3 papers, 2015 to 2021). "A study comparing the expression of TLR2 in middle ear effusion among otitis-prone and non-otitis-prone OME children who underwent ventilating tube insertion showed that expression of TLR2 mRNA was significantly lower in the otitis-prone group." (PMID 34360632, 2021). "This study showed that the expression of TLR6 mRNA was significantly lower in the otitis-prone group than in the non-otitis–prone group, with similar results to those observed for TLR2 mRNA." (PMID 34360632, 2021). "Furthermore, TLR2 deficiency leads to a decreased proinflammatory cytokine profile, including TNF and IL-1β, in a murine model of S. pneumoniae otitis, resulting in increased bacterial outgrowth, bacteraemia and death." (PMID 31700009, 2019). "Susceptibility to otitis might also be impacted by deficiencies in innate immune molecules, such as the microbial pattern recognition receptors Toll-like receptor 4 (TLR4) and Toll-like receptor 2 (TLR2), and the immune signaling molecule MyD88." (PMID 25765466, 2015).
proteinopathy (3 papers, 2020 to 2024). "Although the contribution of intestinal microbiota and TLR2 to PD pathology was validated in genetic PD models, evidence suggests that the effects of TLR2 signaling on proteinopathy might depend on the presence of a genetic etiology." (PMID 38257933, 2024). "Interestingly, TLR2 and TLR4 have also been implicated in other proteinopathies, including Alzheimer’s and Huntington’s disease raising the possibility of a common pathogenic mechanism across several neurodegenerative diseases." (PMID 33272323, 2020). "Furthermore, some studies have also reported that the effects of TLR2 signaling on proteinopathy might depend on the presence of genetic factors." (PMID 38257933, 2024). "Furthermore, it is important to note that the effect of TLR2 on the pathogenesis of proteinopathy might differ between models that recapitulate the genetic etiology and those that do not." (PMID 38257933, 2024).
psoriasis vulgaris (3 papers, 2020 to 2023). Plaque psoriasis is the most common presentation of psoriasis. "It is believed that RS3804099 polymorphism of the TLR2 gene is associated with susceptibility to psoriasis vulgaris in southern China." (PMID 37176151, 2023). "Previous reports showed that TLR2 was increased on peripheral blood monocytes from patients with psoriatic arthritis and that the single nucleotide polymorphism rs3804099 of TLR2 has significant effects on the heritability of psoriasis vulgaris in Chinese people." (PMID 33202847, 2020).
pyelonephritis (3 papers, 2009 to 2021). An inflammatory process affecting the kidney. "During kidney infection, IFNγ stimulation has been shown to increase TLR4 and TLR2 expression in infected kidneys." (PMID 34015044, 2021). "In order to discover novel polymorphisms associated with UTIs, we PCR-amplified and sequenced the coding regions of 7 TLR pathway genes (TLR2, TLR4, TLR5, MYD88, TIRAP, TRIF, and TRAM) in subjects with a high frequency of cystitis or pyelonephritis episodes." (PMID 19543401, 2009).
relapsing remitting MS (3 papers, 2013 to 2021). "For example, the expression of TLR2, TLR4, and TLR9 on CD4+ and CD8+ T cells was significantly higher in patients with relapsing remitting MS (RRMS) than healthy individuals." (PMID 34790205, 2021). "Patients with relapsing-remitting multiple sclerosis (RRMS) have an increased number of neutrophils that regulated phenotypic changes such as reduction of apoptosis and higher expression of TLR2, FPR1, CXCR1, and CD43." (PMID 24174969, 2013). "In addition, relapsing-remitting MS (RRMS) patients show elevated levels of soluble TLR2 (sTLR2), although sTLR2 would not necessarily be pathogenic because it could absorb TLR2 ligands." (PMID 31781124, 2019).
Rotavirus infection (3 papers, 2014 to 2022). Infection with any of the rotaviruses. "Similarly, Toll like receptor 2 (TLR2) ligands have been shown to induce IgA and CCR9 expression in circulating B lymphocytes, and during the course of an acute rotavirus infection both IgA and IgM ASCs express CCR9 and are able to migrate to CCL25." (PMID 27003360, 2016). "It has been shown that the levels of TLR2 and TLR4 on various cells are increased during the initiation and modulation of the immune response to rotavirus infection, and that HMGB1 acts as a pro-inflammatory cytokine that causes persistent inflammatory responses via activation of TLR2 and TLR4." (PMID 24651485, 2014).
subarachnoid hemorrhage (3 papers, 2021 to 2024). A serious neurological disorder characterized by intracranial hemorrhage into the subarachnoid space. "In a rat model of subarachnoid hemorrhage, elevated expression of Panx1 channels exacerbated the inflammatory injury associated with TLR2/TLR4/NF-κB signaling." (PMID 35325354, 2022). "In addition, the Tlr2/Irf7 signaling axis has been associated with microglia-mediated inflammation after subarachnoid hemorrhage in mice." (PMID 38570482, 2024). "In addition, in early brain injury after subarachnoid hemorrhage, inflammatory response mediated by Panx 1 was primarily through the TLR2/TLR4/NF-κB-mediated signaling pathway." (PMID 34475813, 2021).
Thrombocytopenia (3 papers, 2021 to 2023). A reduction in the number of circulating thrombocytes. "Interestingly, TLR2 was also identified as a potential important target in the network pharmacology prediction study of ruxolitinib for thrombocytopenia." (PMID 36555781, 2022). "We found eight proteins (ITGA2B, ITGB3, VWF, PLEK, TNF, TLR2, BCL2 and BCL2L1) were the core targets of DMAG for the treatment of thrombocytopenia." (PMID 34837956, 2021).
trigeminal neuralgia (3 papers, 2022 to 2025). Trigeminal neuralgia is a nerve disorder that causes a stabbing or electric-shock-like pain in parts of the face. "Previous studies have suggested that TLR2 is involved in the pathogenesis of neuropathic pain and trigeminal neuralgia." (PMID 35987639, 2022).
Ureteral obstruction (3 papers, 2009 to 2023). Obstruction of the flow of urine through the ureter. "In the neonatal model of unilateral ureteral obstruction, it is currently unknown how this Tlr2-/- associated apoptotic pathway is activated, caspase-3 might not be involved at all." (PMID 38015955, 2023). "MMP-2 expression increased significantly after ureteral obstruction at d7 and d14 in WT and Tlr2-/- mice, with a slightly increasing trend for Tlr2-/- kidneys, but without significant differences between the two lines." (PMID 38015955, 2023). "The authors measured apoptosis through staining of active caspase-3 in cells, which was significantly reduced in Tlr2-/- mice after 7 days of ureteral obstruction." (PMID 38015955, 2023). "Our study indicates involvement of TLR2 in the mediation of apoptosis in the early life developing murine kidney suffering from ureteral obstruction." (PMID 38015955, 2023). "Thus, newborn Tlr2-/- and wild type (WT) C57BL/6 mice were subjected to complete unilateral ureteral obstruction (UUO) or sham-operation on the 2nd day of life." (PMID 38015955, 2023). "Thus, TLR2 is not involved in pyroptosis after ureteral obstruction in the neonatal kidney." (PMID 38015955, 2023).
vaginal infection (3 papers, 2018 to 2024). "We then tested the effect of the vaginal infection sEVs on PBMCs in the presence of MALP-2, a TLR2/6 ligand derived from mycoplasma, another frequent TV endosymbiont." (PMID 33224901, 2020). "To clarify the role of TLR2 and TLR9 in inflamed tissues after mucosal HSV infection, we assessed the survival of WT, TLR2 KO, TLR9 KO, and TLR2/9 DKO mice following vaginal infection with different doses of the HSV-1 McKrae strain (1 × 106, 1 × 107, and 5 × 107 pfu/mouse)." (PMID 29760708, 2018).
vasculitis (3 papers, 2020 to 2023). "Growing data show that zymosan triggers the innate immune system through stimulation of pathogen recognition receptors, and vasculitis is linked to the activation of the TLR2 signaling pathway induced by zymosan." (PMID 35911646, 2022). "Anti-PCSK9 mAb1 has not yet been investigated for its role in HFD together with zymosan-induced vasculitis through regulation of the TLR2 and NF-ƙB pathway." (PMID 35911646, 2022). "The TLR2 and NF-kB pathway is one of the imperative pathways in the pathophysiology of vasculitis because it involves the activation of a cascade of inflammatory mediators." (PMID 35911646, 2022). "HFD and zymosan administration elevated vasculitis by increasing aortic TLR2 and NF-kB levels, which resulted in a rise in the percentage of plaque area in the aorta, as validated by histological examination of the aorta." (PMID 35911646, 2022). "In conclusion, our research showed for the first time that the anti-PCSK9 mAb1 (6 and 10 mg/kg) treatment attenuated the vasculitis via modulating the TLR2 and NF-ƙB pathway in HFD together with zymosan treated mice." (PMID 35911646, 2022). "It has been proposed that activation of toll-like receptor 2 may trigger an inflammatory pathway leading to vasculitis and endothelial damage to the pancreas." (PMID 37261182, 2023). "Therefore, the current investigation aimed to assess the effects of anti-PCSK9 mAb1 on vascular inflammation in HFD together with zymosan-induced vasculitis via inhibiting the TLR2 and NF-ƙB pathway." (PMID 35911646, 2022). "The goal of the present study was to see whether anti-PCSK9 mAb1 might prevent vasculitis in C57BL/6 mice by blocking TLR2/NF-B activation in HFD and Zymosan-induced vasculitis." (PMID 35911646, 2022).
abdominal aortic aneurysm (2 papers, 2020 to 2023). Enlargement and ballooning of the vessel that supplies arterial blood to the abdomen, pelvis and legs. "Yan and colleagues also found that blocking TLR2 signaling decreases Ang II-induced chronic inflammation and vascular remodeling in models of abdominal aortic aneurysm." (PMID 33318302, 2020). "TLR-2 is also upregulated in patients with abdominal aortic aneurysm (AAA) when compared with healthy individuals; it is currently believed that TLR-2 may be integral at regulating inflammation in the aorta in the context of AAA formation." (PMID 37508529, 2023).
Acanthamoeba keratitis (2 papers, 2016 to 2019). Keratitis due to infection by acanthamoeba; it is usually associated with soft contact lens wear, particularly overnight wear. "isolated from a patient with Acanthamoeba keratitis and from environmental water samples, TLR2 and TLR4 showed increased expression in pneumocytes, interstitial cells, and epithelial cells of the bronchial tree." (PMID 31309100, 2019). "isolated from a patient with Acanthamoeba keratitis (Ac55) and Malta Lake (Ac43), the levels of expression of TLR2 were statistically higher than the levels of expression of TLR4." (PMID 27511368, 2016).
Adenovirus infection (2 papers, 2012 to 2024). "Innate immunity to adenovirus infections involves the TLR2 and TLR9 pathway, and emerging evidence indicates that the inflammasome participates in the antiviral response." (PMID 22928129, 2012).
alcoholic hepatitis (2 papers, 2017 to 2019). Acute hepatitis resulting from ingestion of alcohol. "The overexpressed TLR2, 4, and 9 induced by bacterial products in activated neutrophil mediate the abnormalities of neutrophil function in alcoholic hepatitis." (PMID 31244862, 2019). "Meanwhile, macrophage expressing markers TLR-2, TLR-4, and TLR-8 as well as the chemokine CCL-1 and CCL-18, were detected in both M1 and M2, indicating that a complex interplay between different types of macrophages is implicated in alcoholic hepatitis." (PMID 31244862, 2019). "Importantly, this dysregulation of TLR2/4 signaling was normalized by the treatment of Kupffer cells or PBMCs from patients with alcoholic hepatitis with HA35." (PMID 29142263, 2017).
allergic bronchopulmonary aspergillosis (2 papers, 2015 to 2021). Allergic bronchopulmonary aspergillosis (ABPA) is a rare immunologic pulmonary disorder caused by hypersensitivity to Aspergillus fumigatus, clinically manifesting with poorly controlled asthma and recurrent pulmonary infiltrates. "Interestingly, TLR2 SNPs showed no susceptibility to CCPA but a potentially protective role in allergic bronchopulmonary aspergillosis (ABPA), whereas patients suffering from ABPA had significantly higher frequency of a TLR9 SNP (T-1237C) compared to unaffected controls." (PMID 25420452, 2015).
Arrhythmia (2 papers, 2016 to 2022). Any cardiac rhythm other than the normal sinus rhythm. "As we have shown that cardiac macrophages produce IL-1β and upregulate NLRP3 expression in response to TLR2 stimulation promoted by DM, we tested whether the NLRP3 inflammasome is involved in the DM-induced cardiac electrical disturbances and susceptibility to arrhythmias." (PMID 27882934, 2016).
Arterial thrombosis (2 papers, 2020). The formation of a blood clot inside an artery. "Furthermore, the development of arterial thrombosis was relative to NOD2, TLR2, and TLR9 signalling in platelets as well as TLR2 and TLR4 pathways in endothelial cells." (PMID 33062141, 2020).
arteriosclerosis (2 papers, 2022 to 2023). A vascular disorder characterized by thickening and hardening of the walls of the arteries. "Overexpression of serine protease inhibitor, clade E member 1 (SERPINE1), Toll-like receptor 2 (TLR2), and CC Chemokine ligand 20 (CCL20) were also reported as a significant causative factors in the progression of arteriosclerosis, thrombosis, differentiation of SMCs and perivascular fibrosis." (PMID 37373979, 2023).